CYTIP (cytohesin 1 interacting protein)
Description:
By its binding to cytohesin-1 (CYTH1), it modifies activation of ARFs by CYTH1 and its precise function may be to sequester CYTH1 in the cytoplasm.
Synonyms: CYBR; CASP; PSCDBP; B3-1; HE; CYTHIP
Tractability: PROTAC: ubiquitination databases record sites on it; its protein half-life has been measured.
Gene: Protein-coding gene on chromosome 2 (157,409,360 to 157,491,093, reverse strand). Ensembl gene ENSG00000115165.
Subcellular location: Cytoplasm; Early endosome
Subcellular location (Human Protein Atlas): Cytosol; Nucleoplasm
Gene Ontology:
Molecular function: protein binding
Biological process: regulation of cell adhesion
Cellular component: cell cortex; cytoplasm; cytosol; early endosome
Genetic constraint (gnomAD): Loss-of-function variants: 25 observed, 38.9 expected, observed/expected ratio (o/e) 0.64, 90% interval 0.47 to 0.9. The upper end of that interval is the gene's LOEUF score, 0.9, which puts it in group 3 of 6, group 1 being the genes least tolerant of losing a copy. Missense variants: 409 observed, 433.39 expected, observed/expected ratio (o/e) 0.94, 90% interval 0.87 to 1.02. Synonymous variants: 155 observed, 160.85 expected, observed/expected ratio (o/e) 0.96, 90% interval 0.85 to 1.1.
Homologues: Orthologues: chimpanzee CYTIP (100% identical), macaque CYTIP (91% identical), pig CYTIP (89% identical), rabbit CYTIP (86% identical), rat Cytip (82% identical), mouse Cytip (81% identical), guinea pig CYTIP (77% identical), dog CYTIP (76% identical), tropical clawed frog cytip (47% identical), zebrafish cytip (41% identical), Drosophila melanogaster ssp6 (27% identical), Caenorhabditis elegans gras-1 (14% identical). Paralogues in human: TAMALIN (35% identical).
Diseases named in the same sentence as CYTIP in open-access papers:
CYTIP is named in the same sentence as 11 diseases in open-access papers, as found by Europe PMC text mining. Sharing a sentence is not in itself a finding about the gene and the disease. The quoted sentences say what the papers report.
non-small cell lung carcinoma (2 papers, 2022 to 2023). A group of at least three distinct histological types of lung cancer, including non-small cell squamous cell carcinoma, adenocarcinoma, and large cell carcinoma. "We also note that in non-small cell lung cancer, hypomethylation of the promoter region of the CYTIP gene is associated with the prediction of responsiveness to programmed cell death protein 1 (PD1)." (PMID 35015072, 2022). "Cytohesin 1 Interacting Protein (CYTIP) was reported to exhibit sensitive response to anti-PD-1 therapy, implying its potentiality as responsive biomarkers for anti-PD-1 immunotherapy in non-small cell lung cancer." (PMID 37988195, 2023).
breast carcinoma (1 paper, 2022). "For example, our LR-seq breast cancer transcriptome identified a novel CYTIP isoform originating from an alternative transcription start site supported by proximal CAGE and ATAC-seq peaks." (PMID 35044822, 2022).
HCMV infection (1 paper, 2017). "Since our previous findings in HSV-1-infected mDCs showed a proteasome-dependent pathway of CYTIP degradation, we examined whether a similar mechanism is responsible for CYTIP downmodulation in the context of an HCMV infection." (PMID 28484459, 2017).
melanoma (1 paper, 2023). A malignant, usually aggressive tumor composed of atypical, neoplastic melanocytes. "In another pan-cancer investigation, CYTIP was identified as an immunosenescence gene, that could also be regarded as a biomarker for immunotherapy in melanoma." (PMID 37988195, 2023).
Obesity (1 paper, 2020). Accumulation of substantial excess body fat. "Further research regarding the relation between CYTIP, CECR1 with obesity is clearly needed." (PMID 32684073, 2020).
sarcoma (1 paper, 2022). A usually aggressive malignant neoplasm of the soft tissue or bone. "Furthermore, this study identified specific molecules (C16orf54, CCR8, CYTIP, SAMD3 and TBX21) that can be used as predictors of the risk of progression and therapeutic targets for patients with sarcomas." (PMID 36153483, 2022). "Furthermore, we reveal five targetable antigens (C16orf54, CCR8, CYTIP, SAMD3 and TBX21) by identifying modules associated with the sarcoma immune landscape." (PMID 36153483, 2022).
cancer (4 papers, 2015 to 2023). A tumor composed of atypical neoplastic, often pleomorphic cells that invade other tissues. "For instance, Vanharanta and colleagues recently showed an association between DNA methylation near CYTIP and the survival of disseminating cancer cells." (PMID 32718321, 2020). "Combined with our observations that DNA methylation directly repels HIF binding, this suggests remethylation of the CYTIP promoter as a viable avenue for decreasing cancer dissemination." (PMID 32718321, 2020).
infection (3 papers, 2017 to 2021). The state of being infected such as from the introduction of a foreign agent such as serum, vaccine, antigenic substance or organism. "This study also showed that the impairment in HSV-1-infected DC migration is at least partially mediated by increased adhesion to fibronectin in later time points of infection (16–24 hpi), as CYTIP expression allows the loss of fibronectin adherence in mDCs." (PMID 34895058, 2021). "While CYTIP is rapidly degraded in the context of infection, β2 integrins, such as predominantly lymphocyte function-associated antigen 1 (LFA-1), are activated." (PMID 34895058, 2021). "Infection of DMSO-treated mDCs with either HSV-1 or HSV-2 resulted in a marked reduction of CYTIP protein levels compared to the respective mock condition." (PMID 31963276, 2020). "We demonstrate for the first time that also HSV-2 mediates a proteasomal degradation of CYTIP in mDCs very early upon infection." (PMID 31963276, 2020). "Taken together, our present study demonstrates that HCMV induces a proteasomal degradation of CYTIP in HCMV-positive mDCs early after infection." (PMID 28484459, 2017). "Since it is known that HCMV replicates slower than HSV-1, we analyzed CYTIP downregulation at different time points post-infection." (PMID 28484459, 2017). "Consistent with our data obtained from mDC infection experiments, we observed a strong decrease in CYTIP protein expression in HSV-1- as well as HSV-2-infected HEK293T cells in the absence of any inhibitor, whereas cytohesin-1 protein levels remained stably expressed." (PMID 31963276, 2020). "Combining these data, it is tempting to speculate that the HSV-2-mediated reduction of mDC migration and the induction of mDC adhesion rapidly upon infection are due to CYTIP downmodulation from 4 hpi onwards." (PMID 31963276, 2020). "Moreover, by probing the blots with the αCYTIP hybridoma supernatant, we detected an additional band of approximately 55 kDa that increases upon infection and might constitute post-translationally modified CYTIP protein." (PMID 31963276, 2020). "Regarding other adhesion and non-chemotactic factors, it has been reported that infection of mature human MoDCs with HSV-1 or HSV-2 produces a proteasome-dependent degradation of cytohesin-1 interacting protein (CYTIP), a key regulator of DC motility." (PMID 34895058, 2021).
CYTIP also shares sentences with these, for which no sentence is quoted: tumor (2 papers); clear cell renal cell carcinoma (1); COVID-19 (1).